CDC6 (cell division cycle 6)
Diseases named in the same sentence as CDC6 in open-access papers (continued):
Sharing a sentence is not in itself a finding about the gene and the disease.
cancer (continued). "The results showed that the CDC6 expression in ccRCC tissue is closely related to individual cancer stages, patients’ race, patients’ gender, patients’ age, tumor grades, KIRC subtypes, and lymph node metastasis status." (PMID 34136398, 2021). "Cdc6 has been reported as a potential therapeutic target in many cancer types, and studies on its role in various cancers have been conducted." (PMID 33020506, 2020). "The results indicated that PAR‐Lipo‐mediated gene editing induced more effective CDC6 KO in cancer cells than other types of gene editing, resulting in stronger growth inhibition of the orthotopic liver tumors." (PMID 32714743, 2020). "Targeting CDC6 has also been shown to sensitized cancer cells to ionizing radiation-induced apoptosis, and reversed EMT." (PMID 32792963, 2020). "The protein levels of CDC6 and Ki67, a cell proliferation marker were assessed in the radioresistant cancer cells as well as NPC tumor specimens." (PMID 30158672, 2019). "The data confirmed that CDC6 knockdown significantly sensitized cancer cells to IR-induced apoptosis and senescence." (PMID 30158672, 2019). "CDC6 overexpression in most cancers suggests targeting CDC6 is a promising strategy for cancer therapies." (PMID 31285446, 2019). "The IR sensitivity of tumor xenografts was tested when CDC6 was depleted in the radioresistant cancer cells." (PMID 30158672, 2019). "Targeting CDC6 with siRNA promoted IR-induced senescence, sensitized cancer cells to IR-induced apoptosis, and reversed EMT." (PMID 30158672, 2019). "Since cancer cells with CDC6 overexpression showed premature senescence and retarded cell proliferation, we observed low expression of Ki67 in the PR tumor tissues." (PMID 30158672, 2019). "The most recent TCGA RNA-seq data reveal that CDC6 is overexpressed in most cancers, highlighting the importance of CDC6 deregulation in tumorigenesis." (PMID 31285446, 2019). "CDC6 overexpression has been detected in a number of cancer types, and high levels of CDC6 correlate with poor prognosis in cancer patients and radioresistance in cancer cells." (PMID 30158672, 2019). "After the identification of CDC6 roles in radioresistance, we elevated CDC6 level in the parental cancer cells, or CDC6 was depleted in the radioresistant cancer cells, and observed the switch of cell senescence, EMT, and radiosensitivity." (PMID 30158672, 2019). "From these data, we deduced that the elevation of CDC6 protein, together with the declining Ki67 (CDC6highKi67low), probably is an important prognostic marker of cancer radioresistance." (PMID 30158672, 2019). "And as a result, a cohort of APCCdh1 substrates, including Plk1, Cdc6, Skp2, cyclin A, are eliminated, which eventually helps to amplify and sustain the anti-cancer function of these inhibitors." (PMID 31420536, 2019). "Conversely, CDC6 knockdown significantly promoted cell apoptosis, and promoted more premature cancer cells to typical senescence." (PMID 30158672, 2019). "In a larger pan-cancer set of 4128 TCGA exomes with expression profiling, we identified mutational correlation with expression for additional elements (e.g., near GATA3, CDC6, ZNF217, and CTCF transcription factor binding sites)." (PMID 29354286, 2018). "Apparently and in agreement with the oncogene-induced replication stress model for cancer development, CDC6-driven genomic instability exerted a selective pressure that led to the evolution of the “escaped” cells." (PMID 29321003, 2018). "Cdc6 is prone to being overexpressed in most cancer cells because of dysfunction in the pRb-E2F transcriptional pathway." (PMID 28592805, 2017). "This study uncovered a new function of Cdc6 in regulating cell cycle progression and has important implications in HPV-associated cancers." (PMID 28592805, 2017).
cancer (continued). "Patients whose tumors expressed either Cdc6 or Cdt1 at a high level also had a shorter survival time compared to those whose cancer expressed both Cdc6 and Cdt1 at a low level (Wilcoxon-Gehan test, p = 0.052)." (PMID 28428557, 2017). "This study suggested a new function of Cdc6 in regulating cell cycle progression and has important implications in HPV-associated cancers." (PMID 28592805, 2017). "Cell cycle analysis indicated that Cdc6 depletion led to aberrant progression of cancer cells into G2/M phase under CDDP exposure." (PMID 27246979, 2016). "Over-expression of Cdc6 in human cancers leads to origin hyperactivation, uncoordinated origin firing and replication stress." (PMID 27775084, 2016). "Higher cdc6 expression in cancer tissues were found compared with the paired adjacent bladder tissues (Figure 1A1)." (PMID 27246979, 2016). "A strong correlation between increased Cdc6 expression and reduced E-cadherin (a hallmark of EMT) were observed in various types of human cancers." (PMID 27246979, 2016). "Over-expression of licensing proteins including ORCs, CDC6 and MCMs have been found in certain cancers and can be potentially used as markers for certain malignancies." (PMID 26416244, 2015). "Overexpression of Cdc6 and c-Myc leads to polyploidy and genomic instability in a variety of cancers." (PMID 25051368, 2014). "This cdc6/c-myc transgenic line will be an excellent experimental animal model and an anti-cancer drug screening platform for identifying the potent c-Myc or Cdc6 inhibitor." (PMID 25051368, 2014). "The results revealed that the survival of multiple cancer cell lines was most dependent on CDC6." (PMID 41339304, 2025). "Using a gene effect score of <−1 as a threshold for dependency, CDT1 loss was not tolerated across most cancer cell lines whereas the consequences of CDC6 and DBF4 loss were less broad across the panel." (PMID 40460119, 2025). "Collectively, these findings indicate that CDC6 plays a critical role in human cancer." (PMID 41339304, 2025). "In addition, CDC6 was classified as a cancer-dependent gene in 1099 out of the 1100 cell lines analyzed." (PMID 41339304, 2025). "To determine whether CDC6 functions as a cancer-related gene, we utilized data from the Cancer Dependency Map (DepMap), which includes genome-wide CRISPR loss-of-function screens across multiple cancer cell lines." (PMID 41339304, 2025). "CDC6 plays an important role in multiple stages of cell division, indicating that its abnormal expression may affect this process, leading to cancer." (PMID 39684684, 2024). "Cdc6, a cell growth regulator, is expressed in the quiescent phase (G1 phase) in normal cells but is expressed at all cell cycle stages in cancer cells and enhances cancer cell proliferation." (PMID 38251008, 2024). "CDC6 is overexpressed and acts as a proto-oncogene in various cancers." (PMID 38685067, 2024). "CDC6 promotes the formation of an immune microenvironment in the endometrium and enhances the infiltration of macrophages, which is likely to further facilitate cancer onset via the PI3K-AKT pathway." (PMID 39684684, 2024). "CDC6 plays a key role in controlling DNA replication, making it a focus of research in cancer." (PMID 39052109, 2024). "Here, we found that OTUD6A upregulated CDC6 protein level in several types of cancer cells." (PMID 38685067, 2024). "The effect of CDC6 on the survival rate of patients with cancer remains largely understudied." (PMID 39684684, 2024). "Collectively, these results suggest that NSC-95397-mediated targeting of replication origin assembly through the destabilization of CDC6 could be exploited as a powerful strategy to selectively kill highly proliferative cancer cells." (PMID 39184446, 2024). "This suggests that CDC6 might provide better conditions for cancer cell growth and promote metastasis and deterioration." (PMID 39684684, 2024).
cancer (continued). "Importantly, ectopic expression of CDC6 effectively reduced the defects in cell proliferation of cancer cells and restored the decreased level of chromatin-bound MCM2 in vitro caused by OTUD6A knockdown." (PMID 38685067, 2024). "CDC6 has been recognized as a cancer diagnosis biomarker in various cancers." (PMID 37501932, 2023). "PPI interaction network analysis showed that the CCNF gene, CDK1 gene and CDC6 gene are closely related, indicating that these genes, as key regulators of the G2/M or G1/S checkpoint of the cell cycle, promote the occurrence and progression of many cancers." (PMID 37168372, 2023). "CDC6 levels are high in cancer cells and ESCs due to high E2F-dependent transcription." (PMID 37760529, 2023). "Besides playing a role in cancer-related pathways by regulating the expression of certain oncogenes and cancer suppressor genes such as KRAS, CDC6 promotes cancer progression as it is positively regulated by associated noncoding RNAs (e.g., lncRNA-CDC6)." (PMID 35537781, 2022). "In HCT-116 cells, CDC6 overexpression was associated with the reduction of E-cadherin, indicating CDC6 may have an important role in the metastasis of HPV-associated cancers." (PMID 35173548, 2022). "The seven DEGs (AURKA, BUB1, CDC6, MAD2L1, NDC80, ZWINT, and TIMELESS) coexpressed only in the LC&OC coexpression network have been associated with the acquisition of the hallmarks of cancer." (PMID 36101460, 2022). "In cancer cells, changes in DNA replication have been associated with decreased levels of MCM proteins, and inhibited origin firing, caused by an interaction between HIF1 and CDC6, which loads the MCM helicase complex onto DNA." (PMID 34603285, 2021). "CDC6 (Cell division control protein 6), located at chromosome 17q21.3, plays an important role in the early stage of DNA replication and has unique functions in various malignant tumors." (PMID 34136398, 2021). "Depletion of CDC6 perturbs DNA replication and induces apoptosis in cancer cell lines." (PMID 32792963, 2020). "High expression of CDC6 protein was reported in most cancers." (PMID 33173413, 2020). "CDC6, one of the 10 candidate key genes, plays an important role in the progression of some cancers 16 - 20, but the full role of CDC6 in HCC still remains unclear." (PMID 33173413, 2020). "Similar result was also observed following CDC6 depletion in KRAS positive cancer cells." (PMID 32854236, 2020). "All of the eigth patients with cancer observed cdc6 positive undergone metastasis." (PMID 32249466, 2020). "The results were likely attributable to the higher CDC6 KO efficiency of the PAR‐Lipo complexes than of the other treatments in cancer cells, which was further confirmed by a western blot assay that indicated the lowest expression of CDC6 in the PAR‐Lipo complex‐treated group." (PMID 32714743, 2020). "The present study is to identify the novel roles of CDC6 in cancer cell radiosensitivity." (PMID 30158672, 2019). "Therefore, CDC6 depletion sensitized cancer cells to radiation therapy, and inhibited cell invasion and migration." (PMID 30158672, 2019). "The discovery of deregulation of pre-RC component CDC6 by mTOR signaling might reveal the mechanism of the promotion of genome instability and heterogeneity of cancer cells by the PI3K signaling pathway." (PMID 31285446, 2019). "Since CDC6 overexpression contributed to cancer cell radioresistance, we deduced that CDC6 depletion might sensitize cancer cells to IR-induced cell apoptosis." (PMID 30158672, 2019). "Our discovery that miR-3178 is suppressed by mTOR and targets CDC6 may provide one of the mechanisms of the deregulation of CDC6 in cancers." (PMID 31285446, 2019). "These miRNAs were downregulated in carcinoma tissue, with the exception of hsa-miR-424-3p, which was upregulated, and hsa-miR-195-5p, hsa-miR-196a-5p, and hsa-miR-424-3p had identified seed matches with CDC6." (PMID 29725503, 2018).
cancer (continued). "In the case of hsa-miR-424-3p and CDC6, while both molecules are upregulated in carcinoma tissue as compared to normal mucosa, the miRNA is most likely mitigating the upregulation of the expression of the mRNA by another factor, possibly acting as a buffer to maintain expression homeostasis." (PMID 29725503, 2018). "This study uncovered a new function of Cdc6 that might be involved in regulating cell cycle progression under hypoxia and has important implications in HPV-associated cancers." (PMID 28592805, 2017). "Preferential sensitivity of some cancer cells to Gmnn depletion may involve their overexpression of pre-RC proteins including Cdt1 and Cdc6, which stimulate pre-RC complex re-assembly and re-firing of origins of replication within the same cell cycle." (PMID 29234490, 2017). "Interestingly, the degree of Cdc6 expression seemed to be correlatable with responsiveness of the cancer towards letrozole." (PMID 28428557, 2017). "More importantly, Cdc6 depletion reverses the PTX resistance on cancer cells." (PMID 27611665, 2016). "Therefore, Cdc6-targeting strategy to improve cancer diagnosis and treatment is a promising area, yet needing further exploration." (PMID 27246979, 2016). "Cdc6 may be served as promising target for improving the therapeutic effect of microtubule-poisoning drugs in cancer treatment." (PMID 27611665, 2016). "In addition, Cdc6 is up-regulated in many types of cancer and is correlated with tumor malignant progression." (PMID 27611665, 2016). "So inhibition of Cdc6 may be a new promising strategy to inhibit ATR pathway for killing CDDP-resistant cancer cells." (PMID 27246979, 2016). "ID1 and ID3, associated with cell differentiation, angiogenesis and reported to be increased in several cancers; MAPK8 associated with cell cycle control and cell differentiation and CDC6 a protein involved in DNA replication and which has been implicated in EMT and cancer development." (PMID 25207642, 2014). "Interestingly, mechanisms to explain increased activation of CDC6 in cancer cells are not well known." (PMID 22977174, 2012). "Normal cells and cancer cells have been observed to respond differently to Cdc6 knockdown, but the genetic alterations in cancer cells that might underlie such differences have not been conclusively identified." (PMID 20195506, 2010). "CDC6 is a regulator of the early initiation of DNA replication of cancer cells in the S phase." (PMID 19102762, 2008). "We found seven upregulated genes (MCM10, RAD51-associated protein 1 (RAD51AP1), KIF2C, Y_RNA, FAM64A, CDC6, and CDCA8) and six downregulated genes (ADAMTS8, ATP1A2, MYH1, OGN, OMD, and ZBTB16) in at least two phenotypes containing either ALT high/middle or TEL high/middle regardless the cancer type." (PMID 38763334, 2024). "However, not until recently was the transcriptional regulation of CDC6 extensively linked to the development of cancer." (PMID 31157164, 2019). "However, it remains unknown whether CDC6 overexpression results in DNA damage in human cancer cells." (PMID 31285446, 2019). "However, the role of Cdc6 and Cdt1 in cancer development is less well understood." (PMID 28428557, 2017). "Indeed, high levels of Cdc6 and Cdt1 have been observed in various types of cancer." (PMID 25051368, 2014). "Since several different genetic alterations, each of which leads to excess activity of the initiation proteins Cdt1 and/or Cdc6, can induce re-replication in mammalian cells, it is likely that induction of re-replication is one of the genome-destabilizing processes that can lead to cancer." (PMID 18154680, 2007).
cancer (continued). "Our analysis revealed significant enrichment of several cancer-related pathways, including the G2M checkpoint, E2F targets, mitotic spindle, DNA repair, spermatogenesis, and MYC targets pathways, in the high CDC6 expression group." (PMID 39052109, 2024). "Alterations in pathways controlling replication licensing correlate with active cell proliferation, as evidenced by elevated levels of CDC6, CDT1, and MCM proteins observed in many cancer types." (PMID 39184446, 2024). "To further explore the impact of changes in CDC6 expression on the overall survival (OS) rate of patients with UCEC, we performed a log-rank test on CDC6 in the cBioPortal for the cancer genomics database; the results are expressed as Kaplan–Meier curves." (PMID 39684684, 2024). "Our results confirmed the synergistic effect of ATR/Chk1 inhibitors and gemcitabine in OTUD6A-overexpressing BCa cells, suggesting the possible beneficial effects of targeting ATR/Chk1 in cancers with high expression of OTUD6A and CDC6." (PMID 38685067, 2024). "The findings demonstrated that the hub genes ORC1, CDC6, CHEK1, and MAD2L1 promoted the cell cycle checkpoint signaling, which is essential in cancer progression." (PMID 37945594, 2023). "We recognized two novel genes, CDC6 and ORC1, that play crucial roles in cancer development and progression." (PMID 37945594, 2023). "This investigation has revealed the significant impact of epigenetic changes following the expression of CDC6 and ORC1, highlighting their potential as novel therapeutic targets in cancer treatment." (PMID 37945594, 2023). "Among these, 94 overlapping DEGs were in the two DEG groups, and 85 DEGs were reverse expression, which is involved in microRNA in cancer, while PTEN and CDC6 were key genes according to PPI net analysis." (PMID 36077151, 2022). "It is reported to interact with CDC6 and KAT7/HBO1 to regulate the cell cycle and be a cancer stem cell feature-related gene in LUAD." (PMID 34616428, 2021). "We observed that BRCA1/2 gene alterations were mutually exclusive with amplification of all the oncogenes examined in the breast (CCND1, CCNE1 and CDC6) and ovarian (CCND1, CCNE1 and BRAF) cancer cohorts." (PMID 34389725, 2021). "Several genes, including CCNB1, CDC20, CDC6, PLK1, and PTTG1, had multiple roles as core essential genes, oncogenes, and roles as hallmarks of cancer and in KEGG pathways." (PMID 32040444, 2020). "As BBR has been reported to possess an anti-proliferative effect in cancer cells, we next investigated the effects of BBR on expression of CDC6." (PMID 30894513, 2019). "A database analysis revealed upregulation of CDC6 mRNA expression in tumour compared to normal tissue and a correlation between CDC6 and CHEK1 mRNA expression in human cancers." (PMID 27775084, 2016). "We are first to report that Cdc6 contributes to PTX-induced mitotic slippage and, more importantly, NCTD or Cdc6 RNAi inhibits the slippage and hence reverse the PTX resistance in cancer cells." (PMID 27611665, 2016). "That is to say Cdc6 plays an important role in EMT; gain and maintenance of the properties of cancer stem cells, which were considered to be the key factor of tumor initiation and drug resistance." (PMID 27246979, 2016). "Studies have shown that up-regulation of CDC6, CDC 20, CDC25 family and Bub1 has relationship with human cancers." (PMID 23738901, 2013). "Doxorubicin, a widely used chemotherapeutic agent known to regulate DNA damage, cell-cycle arrest, and apoptosis, can perturb the expression of several cancer driver genes (GADD45B, UHRF1, CDC6, etc.)that are involved in cell-cycle regulation, from this high-throughput data analysis." (PMID 41431699, 2025). "Notably, CDC6 and CDT1 showed lower gDS and PubTator scores, are referred to as Tbio in Target development levels, and positively correlated with cancer-related pathways, which is worthy of further experimental exploration in RCC." (PMID 38728235, 2024).